HPS3 (HPS3 biogenesis of lysosomal organelles complex 2 subunit 1)
Description:
Involved in early stages of melanosome biogenesis and maturation.
Synonyms: SUTAL; BLOC2S1
Tractability: Antibody: the Human Protein Atlas places it where antibodies can reach. PROTAC: ubiquitination databases record sites on it; its protein half-life has been measured.
Gene: Protein-coding gene on chromosome 3 (149,129,618 to 149,173,732, forward strand). Ensembl gene ENSG00000163755.
Subcellular location: Cytoplasm; Cytoplasm, cytosol
Subcellular location (Human Protein Atlas): Golgi apparatus; Plasma membrane
Gene Ontology:
Molecular function: protein binding
Biological process: melanosome assembly; pigmentation; platelet dense granule organization; eye pigmentation
Cellular component: BLOC-2 complex; cytoplasm; early endosome; cytosol
Genetic constraint (gnomAD): Loss-of-function variants: 46 observed, 85.95 expected, observed/expected ratio (o/e) 0.54, 90% interval 0.42 to 0.68. The upper end of that interval is the gene's LOEUF score, 0.68, which puts it in group 2 of 6, group 1 being the genes least tolerant of losing a copy. Missense variants: 1,051 observed, 1,090 expected, observed/expected ratio (o/e) 0.96, 90% interval 0.92 to 1.01. Synonymous variants: 374 observed, 403.8 expected, observed/expected ratio (o/e) 0.93, 90% interval 0.85 to 1.01.
Gene-disease validity (ClinGen):
ClinGen rates the evidence that HPS3 causes each of these diseases.
Hermansky-Pudlak syndrome 3 (autosomal recessive): Definitive.
Homologues: Orthologues: chimpanzee HPS3 (99% identical), macaque HPS3 (98% identical), dog HPS3 (90% identical), pig HPS3 (90% identical), rabbit HPS3 (89% identical), guinea pig HPS3 (82% identical), mouse Hps3 (81% identical), rat Hps3 (78% identical), tropical clawed frog hps3 (53% identical), zebrafish hps3 (37% identical), Drosophila melanogaster CG14562 (19% identical).
Diseases named in the same sentence as HPS3 in open-access papers:
HPS3 is named in the same sentence as 18 diseases in open-access papers, as found by Europe PMC text mining. Sharing a sentence is not in itself a finding about the gene and the disease. The quoted sentences say what the papers report.
oculocutaneous albinism (5 papers, 2013 to 2022). Oculocutaneous albinism (OCA) describes a group of inherited disorders of melanin biosynthesis characterized by a generalized reduction in pigmentation of hair, skin and eyes and variable ocular findings including nystagmus, reduced visual acuity and photophobia. "Variants in the human HPS3 gene cause Hermansky–Pudlak syndrome 3, which involves a mild form of oculocutaneous albinism and prolonged bleeding time." (PMID 32526956, 2020). "Genetic variants in HPS3 are known to cause Hermansky–Pudlak syndrome type 3 (HPS3) in humans, which is a rare autosomal recessive disorder characterized by oculocutaneous albinism and a bleeding disorder with storage pool deficiency due to the absence of platelet-dense bodies." (PMID 32526956, 2020).
Hermansky-Pudlak syndrome (4 papers, 2007 to 2021). Hermansky-Pudlak syndrome (HSP) is a multi-system disorder characterized by oculocutaneous albinism, bleeding diathesis and, in some cases, neutropenia, pulmonary fibrosis, or granulomatous colitis. "Interestingly, two genes associated with the Hermansky-Pudlak syndrome, HPS3 and Rab38, a small GTPase of the Rab family expressed in bronchial and alveolar epithelial cells, were increased in the “rapid” progressors group." (PMID 17534432, 2007).
bleeding disorder (2 papers, 2020 to 2021). "As the signs concerning bleeding disorders of HPS3 in humans are mild, it cannot be excluded that subtle clinical signs in dogs were overlooked." (PMID 34356108, 2021).
inflammatory bowel disease (2 papers, 2021 to 2025). A spectrum of small and large bowel inflammatory diseases of unknown etiology. "However, no phenotype of inflammatory bowel disease or pulmonary fibrosis in HPS3 mutations has been reported in the literature." (PMID 34608437, 2021).
Nystagmus (2 papers, 2021). Rhythmic, involuntary oscillations of one or both eyes related to abnormality in fixation, conjugate gaze, or vestibular mechanisms. "Furthermore, HPS3 in humans is characterized by ocular findings such as nystagmus, reduced visual acuity and a mild bleeding tendency caused by the absence of platelet dense granules." (PMID 34356108, 2021). "In this study, we identified a novel homozygous frameshift mutation (NM_032383.5, c.1231dupG/p.Aps411GlyfsTer32) of HPS3 in a consanguineous family that presented with typical HPS phenotypes such as albinism, visual impairment, nystagmus, pulmonary fibrosis, and bleeding diathesis." (PMID 34608437, 2021). "In summary, the present study identified a novel HPS3 homozygous mutation (c.1231dupG/p.Aps411GlyfsTer32) in a consanguineous family presented with typical HPS phenotypes including albinism, visual impairment, nystagmus, and bleeding diathesis." (PMID 34608437, 2021).
pulmonary fibrosis (2 papers, 2021 to 2024). Chronic progressive interstitial lung disorder characterized by the replacement of the lung tissue by connective tissue, leading to progressive dyspnea, respiratory failure, or right heart failure. "In contrast, in HPS3 mice, a subtype that has not been associated with pulmonary fibrosis, AT2 cell numbers were comparable to WT at 8 and 24 weeks of age." (PMID 39699958, 2024).
Hypertension (1 paper, 2021). The presence of chronic increased pressure in the systemic arterial system. "The functions of HPS3, FASTKD3 and FIGNL1 have no direct or indirect association with the pathogenesis of hypertension, and the existing studies have not proved their association with hypertension." (PMID 34297769, 2021). "HPS3, FASTKD3 and FIGNL1 1 are not directly or indirectly associated with hypertension." (PMID 34297769, 2021).
lysosomal disorder (1 paper, 2009). "Patients with HPS type 3, and mutant in HPS, usually have mild symptoms and mice mutated in the orthologous gene (Hps3) have the cocoa phenotype which produces a lighter coat colour and prolonged bleeding time but does not have a lysosomal disorder." (PMID 20042077, 2009).
ocular albinism (1 paper, 2021). Albinism affecting the eye in which pigment of the hair and skin is normal or only slightly diluted. "For IP1 with the compound heterozygous variants in HPS3 a specialized ophthalmological examination showed ocular albinism." (PMID 35126127, 2021).
ulcerative colitis (1 paper, 2025). An inflammatory bowel disease involving the mucosal surface of the large intestine and rectum. "Overall, we presented a rare case of HPS3-related IBD characterized by more severe ulcerative colitis symptoms than previously reported." (PMID 40176789, 2025).
HPS3 also shares sentences with these, for which no sentence is quoted: albinism (1 paper); Chediak-Higashi syndrome (1); Griscelli syndrome (1); Hermansky-Pudlak syndrome type 3 (1); Menkes syndrome (1); oculocutaneous albinism type 1 (1); pericardial effusion (1); X-linked ocular albinism (1).